TLR7 (toll like receptor 7)
Diseases named in the same sentence as TLR7 in open-access papers (continued):
Sharing a sentence is not in itself a finding about the gene and the disease.
influenza (continued). "Thus, AEP activity is critical for TLR7 processing, opening new possibilities for the treatment of influenza and TLR7-dependent inflammatory diseases." (PMID 22916010, 2012). "Because of TLR7 ability to promote a Th1 biased response, it is possible that the inclusion of TLR7 ligands may enhance the immunogenicity of influenza vaccines." (PMID 21966467, 2011). "Thus, the authors proposed a model, now known as the exogenous pathway, whereby pDCs endocytose and degrade a portion of incoming influenza virions, allowing TLR7 to engage exposed genomic RNA." (PMID 21994762, 2011). "We confirmed the role of TLR7 in the recognition of whole inactivated influenza vaccines." (PMID 21998693, 2011). "We would like to thank Dr. Akiko Iwasaki of Yale University, New Haven, CT and Regeneron Pharmaceuticals, Inc, Tarrytown, NY for proving TLR7 gene knock-out mice, as well as Dr. Andrew Gewirtz of Emory University and Dr. Nancy Cox of Influenza Division for their helpful suggestions and support." (PMID 21966467, 2011). "Results with R848 werequalitatively similar (LPAFAT/LPAFAT2 mRNA expression, PAFR-dependency ofinflammation) to that observed after Influenza infection, suggesting that activationof TLR7/8 is a main mechanism by which Influenza infection leads PAF release andPAFR activation." (PMID 21079759, 2010). "Therefore, of the known major recognition receptors for Influenza,it appears that TLR7/8 is the one capable of inducing LPAFAT/LPAFAT2 expression andtriggers pulmonary inflammation in PAFR-dependent manner." (PMID 21079759, 2010). "Robust responses to influenza vaccine in non-obese females are associated with higher Aicda gene expression and somatic hypermutation; and increased expression of the X-linked Tlr7 gene in the splenic B cells, regulated by increased DNA methylation." (PMID 41488663, 2025). "However, the inclusion of a TLR7/8 agonist resulted in higher influenza-specific IgG in females." (PMID 38675797, 2024). "Hence, TLR7 antagonism reduces diverse types of cytokine storm in severe influenza." (PMID 34473195, 2021). "Therefore, our results may be useful in improving the immunogenicity of split-virion influenza vaccines using pancreatic dendritic cell-activating adjuvants that could improve the intrinsic TLR7 signalling in B cells." (PMID 32094377, 2020). "Our data demonstrate that platelet-TLR7-driven responses lead to C3 release during influenza infection and consequently, C3 augments the release of DNA from neutrophils and promotes the formation of platelet–neutrophil aggregates which may contribute to influenza-mediated increased risk of MI." (PMID 30992428, 2019). "It is unknown whether platelets contribute to overall neutrophil activation through other TLRs (e.g., TLR7 which becomes activated by viral ligand) during influenza infection or if the platelet–neutrophil relationship becomes pathologically imbalanced during infection." (PMID 30992428, 2019). "Therefore, we speculate that XJXRY may exert anti-influenza and anti-inflammatory effects by down-regulating key factors (i.e., TLR7, MyD88 and NF-κBp65) of the TLR7 signaling pathway." (PMID 31572491, 2019). "However, as TLR7 is nonessential for the production of pro-inflammatory cytokines/chemokines and development of protective immunity toward primary influenza A infection in mice, TLR7 is likely dispensable also for influenza-induced recruitment of MCp to the lung." (PMID 30337928, 2018). "We have previously shown in a randomized clinical trial that the topical application of a toll-like receptor 7 agonist, imiquimod, just before intradermal influenza vaccine could expedite and augment antibody response, including to antigenically-drifted strains." (PMID 30369932, 2018). "Interestingly, RIG-I and MDA-5 increased to a higher change than TLR3 and TLR7 at 6 hpi, suggesting RLRs might play more vital roles in sensing RNA at early stage of influenza infection than TLRs." (PMID 26008703, 2015).
influenza (continued). "TLR3, TLR7, TLR9, and RIG1 are known to be involved in sensing influenza viral antigens and activating downstream signaling pathways." (PMID 39846844, 2025). "The synthetic combinations of TLR7 and TLR4 agonists, when administered with recombinant or chimeric hemagglutinin (rHA), significantly enhanced cross-protection against diverse influenza strains." (PMID 41012165, 2025). "αVβ6 activated lysosomal autophagy machinery to remove TLR7, leading to the suppression of TLR7-mediated IFN signaling against Influenza infection." (PMID 38915411, 2024). "Therefore, split influenza vaccination alone is unlikely to cause FT1D through the TLR-7 pathway." (PMID 37140990, 2023). "TLR3, TLR7, TLR8, and RIG-I are known to be involved in sensing influenza viral Ags and activating downstream signaling pathways." (PMID 38112660, 2023). "TLR7 and TLR8 involving in viral sensing play a central role in the vaccine response to trivalent influenza vaccine (TIV) in adults within 24 h after immunization." (PMID 36804941, 2023). "To verify that FTA treatment produces efficacy through TLR7 signaling in lung immune cells, we infected TLR7-/- mice with the FM1 influenza strain and treated them with FTA." (PMID 35733131, 2022). "The ability of TLR7/8 to reduce replication of viruses has been demonstrated in HIV-1, influenza, and MERS-CoV, as upon entry into the cell viral ssRNA binds to TLR7/8 promoting activation and antiviral immunity." (PMID 33498183, 2021). "In mouse hepatitis coronavirus, CD200R inhibits TLR7 signaling, dampening type I IFN production in response to TLR7 ligands, and in mouse influenza CD200R decreases inflammation during pulmonary infection." (PMID 33780466, 2021). "A549 cells infected with influenza and treated with curcumin showed inhibition of influenza-induced expression of TLR2, TLR4, and TLR7, as well as inhibition of activation of MyD88- and TRIF-dependent signaling pathways." (PMID 34282358, 2021). "TLR7 and IFN-α have been shown to have important roles in the induction of antibody-class switching and generation of high-affinity antibody against influenza and other viruses." (PMID 32094377, 2020). "Ducks utilize many of the same PRRs to detect influenza, namely RIG-I, TLR7, and TLR3 and their downstream adaptors." (PMID 32477965, 2020). "Changes in expression of different toll-like receptors (TLRs) (TLR2, TLR3, TLR4, TLR7, TLR8, and TLR9) have been reported before in human monocytes and dendritic cells from seasonal influenza infected patients." (PMID 30682165, 2019). "TLR7 and TLR8 have been recently identified as important sensors of ssRNA from the viral genomes of influenza, vesicular stomatitis virus, and the human and simian immunodeficiency viruses, HIV and SIV28." (PMID 28128342, 2017). "TLR7 and TLR8 are related phylogenetically and functionally and have been identified as important sensors of ssRNA from the viral genomes of influenza and vesicular stomatitis virus as well as HIV itself." (PMID 26154133, 2015). "Here, we describe the role of the innate pattern recognition receptor TLR7 in WIV-mediated induction of CTL responses and heterosubtypic cross-protection against influenza infection." (PMID 23658804, 2013). "Tlr7 exhibits variable XCI escape and can result in higher expression in B cells which promotes class‐switch recombination to IgG2c, which enhances humoral responses against influenza." (PMID 41574968, 2026). "The present report demonstrates that surface charge and composition of liposomal formulations of the TLR7/8 agonist INI-4001 are crucial in shaping their biocompatibility as well as humoral and cell-mediated immunogenicity when combined with the influenza antigen H7." (PMID 40660065, 2026). "Though we did not measure levels of Tlr7 gene expression in this study, we previously showed that Tlr7 has greater expression in B cells from wild-type females than males following influenza vaccination." (PMID 38441028, 2024).
influenza (continued). "We tested influenza vaccination in a mouse model with two adjuvants: Sendai virus-derived defective interfering (SDI) RNA, a RIG-I agonist; and an amphiphilic imidazoquinoline (IMDQ-PEG-Chol), a TLR7/8 agonist." (PMID 38711520, 2024). "In another study, administration of a licensed quadrivalent inactivated influenza vaccine adjuvanted with RIG-I (SDI-nanogel) and a TLR7/8 agonist (imidazoquinoline) enhanced the antibody and T cell responses and was correlated with protection against lethal influenza virus infection." (PMID 38892096, 2024). "The induction of type I IFN needs to be tightly controlled, as it was shown in healthy individuals that inhalation of a TLR7 agonist was initially well tolerated after the first dose, but led to an increased TNF-α and IFN I response and influenza-like symptoms, after a second dose." (PMID 36978183, 2023). "In another study, a licensed quadrivalent inactivated influenza vaccine (QIV) administered with RIG-I (SDI-nanogel) and TLR7/8 agonist (Imidazoquinoline) enhanced antibody and T cell responses, correlating with the protection against lethal influenza virus infection." (PMID 38179453, 2023). "Thus, unlike the progenitor ABC which develop independently of both foreign Ag and TLR7 and TLR9 pathways, the iABC response to influenza infection is highly dependent on both endosomal TLR7 and TLR9 pathways." (PMID 36056604, 2022). "Freshly isolated PBMCs before and after influenza vaccination of the volunteers were stimulated ex vivo with heat-inactivated SARS-CoV-2, heat-inactivated Influenza H1N1, poly(I:C) (TLR3 ligand), and R848 (TLR7/8 ligand)." (PMID 34695164, 2021). "Moreover, in influenza infection, viral entry, uncoating, and endosomal acidification were required for cytokine induction by human neutrophils via TLR8 and TLR7 signaling." (PMID 33003471, 2020). "The inhibition of TLR7 reduced influenza-mediated DNA release from neutrophils but not to the full extent." (PMID 30992428, 2019). "In mice, influenza infection is sensed by toll-like receptor 3 (TLR3), TLR7, retinoid acid-inducible gene I (RIG-I), melanoma differentiation associated protein 5 (MDA-5), and the NOD-like receptor family member NOD-, LRR- and pyrin domain-containing 3 (NLRP3)." (PMID 30337928, 2018). "(A) Quantification of IFNα and TNFα in supernatants of human pDCs cocultured with DENV-infected (DENV cells) or uninfected BHK-21 cells (Mock), in presence of synthetic TLR7 agonist: Imiquimod; IMQ; 1 μg/mL or influenza infectious supernatant; Flu; 3 × 103 FFU." (PMID 29914621, 2018). "Taken together this evidence indicates that TLR7 plays an important role in the primary response to influenza, but is not essential to the development of a memory response." (PMID 29552008, 2018). "Moreover, TLR7 and IFN-α can act together and induce the switching of B cells to IgG2a/c during influenza infection." (PMID 27362648, 2016). "For instance, stimulation of other pattern recognition receptors that respond to influenza, such as TLR3, TLR7, and RIG-I, could affect pneumococcal transmission, as shown for TLR2." (PMID 25166617, 2014). "It was shown that TLR3, TLR7 and MyD88 signaling is not required for efficient T responses during influenza infection, but both TLR7 and MyD88 are critical for B cell responses during influenza infection." (PMID 25539593, 2014). "Vaccination of TLR7−/− mice with influenza WIV failed to protect against a lethal heterosubtypic challenge; in contrast, wild-type mice were fully protected." (PMID 23658804, 2013). "TLRs, such as TLR3, TLR7, and TLR8, are membrane-bound PRRs that recognize viral RNA: TLR3 detects double-stranded RNA (dsRNA), a byproduct of influenza replication, TLR7/8 sense single-stranded RNA (ssRNA) from the viral genome, while TLR2 and TLR4 recognize influenza-induced DAMPs." (PMID 40692679, 2025).
influenza (continued). "If the non-specific protection provided by OPV (the live-attenuated polio virus) against influenza and SARS-CoV-2 viruses is through stimulation of TLR-7 and -8, it might also confer protection against another RNA virus, e.g., the human immunodeficiency virus (HIV)." (PMID 39534998, 2024). "Therefore, heightened expression of TLR-7 by immune cells in female lymphoid tissues, coupled with the subsequent stimulation by LAIV, could contribute to the higher influenza-specific antibody magnitude in both pediatric and adult female-derived organoids." (PMID 38812520, 2024). "In another study, a TLR7/8 agonist (imidazoquinoline) combined with the H5N1 HA antigen was shown to broaden the antibody response in mice and ferrets and protect against homologous and heterologous virus challenges in ferrets, suggesting the increased efficacy of this influenza vaccine." (PMID 38892096, 2024). "This study shows that in severe influenza, TLR7 antagonist treatment ameliorates both type I interferon–driven and interferon-independent immunopathology by blocking TLR7-dependent cytokine production by immune cells, without affecting RIG-I–dependent responses in lung epithelia." (PMID 34473195, 2021). "Lipidated TLR7/8 adjuvants drove a predominantly IgG2a influenza-specific response compared to non-adjuvanted A/Vic as evidenced by the fact that IgG2a titers were increased more than IgG1 titers by adjuvanting with UM-3003, -3004, and -3005 compared to A/Vic alone." (PMID 32210973, 2020). "TLR7 specificity is confirmed in murine models lacking the receptor, and platelet depletion models support platelet-mediated C3 and neutrophil-DNA release post-influenza infection." (PMID 30992428, 2019). "TLR4 contribution was not demonstrated in TLR4 KO mice with influenza infection, thereby affirming the predominant involvement of TLR3 and TLR7 activation in response to influenza virus." (PMID 38835761, 2024). "However, it has been shown that TLR7/8 potentiates rather than activates oxylipin synthesis, notably on subsequent stimulation by fMLP, platelet-activating factor, and the ionophore A2318734 suggesting that in our influenza stimulation model, only TLR3/MDA5 has been engaged in the oxylipin response." (PMID 37575177, 2023). "Toll-like receptor 7 (TLR7) plays a vital role in the immune response to ssRNA viruses such as human rhinovirus (HRV) and Influenza, against which there are currently no treatments or vaccines with long term efficacy available." (PMID 25211222, 2014). "The natural ligand of TLR7 is single stranded (ss) RNA; viral ssRNA is an intrinsic component of WIV, but not of other influenza vaccines." (PMID 23658804, 2013). "Therefore, antagonizing TLR7-dependent IFN-I production by pDCs and monocytes is a promising strategy to dampen inflammation in severe influenza cases without losing antiviral protection by epithelial-derived IFN-I." (PMID 34473195, 2021). "While in some immune cells TLR7 is the major PRR mediating IFN induction by influenza virus, we found that the absence of TLR7 or its downstream adaptor MyD88 had no impact on the induction of IFNs in influenza-infected epithelia." (PMID 24278020, 2013). "Interestingly, a recent study investigating the immunogenicity of various inactivated influenza vaccines has reported that whole β-propiolactone inactivated H5N1 preparations, but not subunit vaccines, trigger IFN-I responses via TLR7 recognition of viral ssRNA." (PMID 21998693, 2011).
asthma (67 papers, 2010 to 2025). "As such, defects in TLR7 expression or function are overrepresented in individuals with asthma, resulting in enhanced IgE and Th2 responses underlying the disease." (PMID 40143355, 2025). "For example, a study found that an increased frequency of TLR7 gene polymorphisms is correlated with a higher risk of asthma in preschool children following infant bronchiolitis." (PMID 40672946, 2025). "Our test results are thus consistent with those of the GEO dataset, and TLR7 has a satisfactory diagnostic ability for asthma." (PMID 38341589, 2024). "Toll-like receptor 7 (TLR7), a candidate gene that was found to be closely associated with immune infiltration in asthma, was also validated in another GEO dataset and induced sputum samples of asthmatic patients." (PMID 38341589, 2024). "The GSE147878 dataset confirmed that the TLR7 expression level in asthma is also significantly reduced and has good diagnostic value." (PMID 38341589, 2024). "Our study reveals that spurious transcripts in Tet3-deficient mouse SMCs lead to activation of TLR7/8 signaling-dependent innate immune responses and massive lung inflammation, resembling human asthma, offering perspectives to treat various lung diseases." (PMID 36539616, 2023). "The role of TLR7 in AR and asthma is often associated with an attenuation of the airway inflammation." (PMID 37426425, 2023). "The potential to be risk genes in asthma development and related atopic disorders was previously shown based on rs179008 in TLR7 and rs2407992 in TLR8, which showed the highest functional significance." (PMID 37426425, 2023). "TLR7 deficiency leads to impaired innate immune responses to RV in asthma, and blocking hsa-miR-150, hsa-miR-152, and hsa-miR-375 was shown to restore TLR7 and IFN responses." (PMID 36366542, 2022). "Previous studies have reported on the genetic variability and functional defects associated with TLR‐7 in cases of asthma." (PMID 33236850, 2021). "Asthma ever was more common (34.6%) in girls with the TLR7 variant AT or TT genotype versus those who were homozygous for the major allele A (12.5%) (p = 0.03)." (PMID 28592890, 2017). "Genetic variation in TLR7 have been associated with the development of asthma, rhinitis, and AD in a Danish population and also with skin-prick test response for house dust mites in a Singaporean Chinese population." (PMID 28228119, 2017). "In conclusion, polymorphism in the TLR10 gene seems to increase the risk of post-bronchiolitis asthma in preschool-aged children, and polymorphism in the TLR7 gene seems to increase the risk of post-bronchiolitis asthma in preschool-aged girls." (PMID 28592890, 2017). "TLR7 has also raised interest in asthma because respiratory viruses are a major cause of exacerbations." (PMID 27014274, 2016). "This difference in TLR7 activity could be a reason why males are more susceptible to asthma and wheezing following RSV infection." (PMID 40143355, 2025). "Moreover, secondary infection of TLR7-deficient mice induced the cardinal features of asthma, including AHR, airway remodeling (e.g., smooth muscle hyperplasia), and airway inflammation." (PMID 28261214, 2017). "Secondly, asthma ever was more common in girls who had the variant TLR7 rs179008 genotype." (PMID 28592890, 2017). "Polymorphism in the TLR10 gene increases and in the TLR7 gene may increase the risk of asthma in preschool-aged children after infant bronchiolitis." (PMID 28592890, 2017). "Since this region has earlier been associated with asthma and AR in a Danish linkage study and since TLR7 agonists have shown beneficial effects both in allergic asthma and in allergic rhinitis, this speaks strongly in favour of this region being truly involved in the development of AR." (PMID 22857391, 2012). "TLR7 may confer predisposition to asthma and related atopic diseases." (PMID 38341589, 2024).